DCX (doublecortin)
Diseases named in the same sentence as DCX in open-access papers (continued):
Sharing a sentence is not in itself a finding about the gene and the disease.
ischemic stroke (16 papers, 2015 to 2026). A stroke disorder caused by obstruction of blood flow to the brain, due to thrombotic (local blood clot formation) or embolic (due to a blood clot or other material traveling from another site) event. "We determined the effect of modulation of glial scar stiffness on neurological recovery after ischemic stroke by quantifying the numbers of EdU+DCX+ and EdU+CD31+ cells in the peri-infarct area of GFAP-ChR2 and GFAP-Arch mice." (PMID 41346705, 2026). "To directly compare the neurogenic potential of iNSPCs from the neonatal and adult brain after ischemic stroke, we investigated the expression patterns of doublecortin (DCX)." (PMID 38534363, 2024). "Although Tbx18-tdT+ cells can generate a small number of Sox2+ i-NSCs following ischemic stroke at both 1 and 3 dpi, they barely produce DCX+ neuroblasts and Olig1+ OL lineage cells." (PMID 39431007, 2024). "Ischemic stroke dramatically increased BrdU+/DCX+ and BrdU+/NeuN+ cells in the DG, SVZ, ischemic cortex, and ischemic striatum." (PMID 37189692, 2023). "To explore the effect of ASIC1a knockout on neurogenesis after ischemic stroke, we performed double immunostaining of DCX and 5-bromo-2-deoxyuridine (BrdU) among LV and along the rostral migratory stream (RMS)." (PMID 37275123, 2023). "To explore whether endogenous neurogenesis was promoted by BHD and/or TPA treatments at day 3 after the ischemic stroke, we used doublecortin (DCX, a marker of newborn neuroblasts) to assess the endogenous neurogenesis." (PMID 26492191, 2015). "After ischemic stroke, adult SVZ NSCs are activated to proliferate and differentiate toward doublecortin (DCX) -expressing neuroblasts, which are capable of migrating into the infarcted regions." (PMID 37252187, 2023). "It was demonstrated that ischemic stroke increased Nestin+ cells in SVZ and DCX+/DAPI in both SVZ and DG (p < 0.01)." (PMID 34220506, 2021). "Thus, the numbers of DCX+/BrdU+ and NeuN+/BrdU+ cells in the SVZ, DG, and ischemic areas of 0.7 g/kg/day ethanol-fed mice under physiological conditions and following ischemic stroke were counted to evaluate the impact of LAC on neurogenesis." (PMID 37189692, 2023). "Furthermore, the immunohistochemistry staining of DCX/BrdU and Sox2/Nestin showed As IV could promote hippocampal neurogenesis and NSC proliferation after ischemic stroke, as well as in vitro." (PMID 32317974, 2020). "Together, these results indicated that administration of 70 mg/kg ambroxol could increase the percentage of DCX+ cells, while decrease the portion of GFAP+ cells in penumbra, to some degree, induced by ischemic stroke, and finally reduced infarct volume to potentiate functional recovery." (PMID 33551744, 2020).
prostate carcinoma (16 papers, 2017 to 2026). A carcinoma that arises from epithelial cells of the prostate gland. "Compared with benign tissues, human prostate cancers are strongly correlated with DCX+ cell density and tumor aggressiveness, with high-risk tumors harboring more DCX+ cells." (PMID 40243726, 2025). "In prostate cancer, the reported stromal expression of DCX was strongly associated with histological grade and clinical outcome, by using immunofluorescent staining to identify stromal DCX + cells." (PMID 39232464, 2024). "The identification of doublecortin (DCX)-positive cells within the stroma of primary human prostate cancers, which also express markers such as PSA-NCAM and Internexin, reinforces this assertion." (PMID 41601691, 2026). "Recent observations in prostate cancer mouse models have suggested that tumour cells can recruit neural progenitor cells expressing doublecortin (DCX) from the central nervous system (CNS)." (PMID 39232464, 2024). "In mouse models of prostate cancer, oscillations of DCX+ neural progenitors in the subventricular zone (a neurogenic area) disrupt the blood–brain barrier, allowing DCX+ cells to enter circulation." (PMID 37566075, 2023). "In the central nervous system, neural progenitor cells that express doublecortin (DCX) infiltrate prostate cancer and metastases and initiate neurogenesis." (PMID 36675991, 2022). "In mouse models of prostate cancer, neural progenitors expressing doublecortin (DCX+) in the subventricular zone, egress into the circulation through disrupting the blood–brain barrier." (PMID 33846291, 2021). "In the periphery, DCX+ progenitor cells are capable to stimulate tumor initiation, tumor growth, and metastasis of prostate cancer cells." (PMID 33142779, 2020). "22.2% of prostate cancer tissues reported were positive of DCX as either low or in moderation while 26% of the liver cancer tissues reported were immunopositive of DCX ranging from high to low." (PMID 28701917, 2017). "The Human Protein Atlas database reported DCX to be moderately expressed in liver and prostate cancer tissues." (PMID 28701917, 2017). "A recent study in prostate cancer suggested that the tumour microenvironment may influence cancer progression by recruitment of Doublecortin (DCX)-expressing neural progenitor cells (NPCs)." (PMID 39232464, 2024). "In a mouse model of prostate cancer, the orthotopic transplantation of DCX+ neural progenitor cells promoted the initiation of both tumor growth and metastasis, whereas the selective depletion of DCX+ progenitor cells suppressed both processes." (PMID 38334648, 2024). "In addition to being a marker of neural progenitor cells, DCX is expressed in a variety of cancers, including glioblastomas, gangliogliomas, prostate cancer, and liver cancer." (PMID 38334648, 2024). "Hence, the genetic depletion of DCX+ cells inhibit the prostate cancer progression, whereas DCX+ cells transplantation promotes prostate tumor growth and metastasis." (PMID 33846291, 2021). "Moreover, in prostate cancer, it has been shown that doublecortin (DCX+) neural progenitors escape the blood–brain barrier to infiltrate the tumor and generate new adrenergic neurons." (PMID 33466373, 2021). "Thus, the authors described the presence within the TME of prostate cancer of nerve cells expressing doublecortin (DCX+), which is a classical marker of neural progenitors from the central nervous system." (PMID 33142779, 2020). "Moreover, in mouse models of prostate cancer, the reduction of DCX + neural progenitors in the sub-ventricular zone was associated with disruption of the blood–brain barrier and the entry into the circulation of DCX + cells that infiltrate the tumor and generate new adrenergic neurons." (PMID 35441960, 2022). "for prostate cancer, by use of transgenic mice with selective genetic depletion of DCX + cells, this has not been demonstrated in breast cancer." (PMID 39232464, 2024).
Cerebral ischemia (15 papers, 2015 to 2024). Restriction of arterial blood supply to the brain associated with insufficient oxygenation to support the metabolic requirements of the tissue. "BrdU+/Nestin+ and BrdU+/DCX+ cells are located in different but overlapping regions, indicating that cerebral ischemia stimulated obvious proliferation of endogenous neuroblasts." (PMID 39090706, 2024). "Next, we applied double labeling for BrdU and DCX to label the newly generated immature neurons in the SGZ 14 days after cerebral ischemia." (PMID 35146924, 2022). "Researchers reported that PNS treatment enhanced DCX+ expressions in the olfactory bulb at day 14 after global brain ischemia/reperfusion." (PMID 35770087, 2022). "In accordance with our previous studies, cerebral ischemia-induced cell proliferation was enhanced, and DCX, an immature neural marker, was expressed in the proliferating cells in the present study." (PMID 27866373, 2017). "The BrdU- and DCX-positive cells were increased in the ipsilateral SVZ following cerebral ischemia compared with the contralateral SVZ following MCAO." (PMID 25617620, 2015). "However, an increase in DCX immunostaining was readily visible in the ischemic cortex at 7 dpi, indicating that cerebral ischemia in cortex stimulates neurogenesis." (PMID 32818074, 2020). "DCX expression may also increase due to neuroinflammation events; for example, in models of cerebral ischemia in mice, colocalization between the DCX and Toll-like receptor 2 (TLR2) and between this receptor and cells positive for the microglial marker IBA-1, have been described." (PMID 37631975, 2023). "Cerebral ischemia stimulates cell proliferation in the SVZ and multiply the number of migrating neurons which express DCX that into the nearby lesioned area." (PMID 32742258, 2020). "After cerebral ischemia, ALK5 colocalized with Nestin (neural stem cell marker) and colocalized with DCX (neuroblast and immature neuron marker)." (PMID 31043581, 2019). "Salidroside was found to increase numbers of BrdU+/Nestin+/DCX+ cells in SVZ region, suggesting that salidroside may promote neuroblast proliferation after cerebral ischemia." (PMID 39090706, 2024). "Although no significant statistical difference was observed in DCX expression between the pMCAO + Vehicle group and the sham group 7 days after cerebral ischemia (p > 0.05), the pMCAO + Vehicle group presented an increasing tendency compared to the sham group." (PMID 35146924, 2022). "In sham group, almost few BrdU/Nestin and BrdU/DCX were found in DG, however, both the numbers of BrdU/Nestin and BrdU/DCX were remarkably increased in damaged DG zone of ME rats, demonstrating that the proliferation and migration of NSC/NPC were triggered in response to cerebral ischemia." (PMID 35770087, 2022). "Besides, both the double-positive cells of BrdU/Nestin and BrdU/DCX in PNS 120 mg/kg group were significantly upregulated compared with ME rats, showing that PNS owned the ability to promote NSC/NPC proliferation and migration after cerebral ischemia." (PMID 35770087, 2022).
X-linked lissencephaly (15 papers, 2009 to 2025). "Previous reports have linked DCX, a causative gene for X-linked lissencephaly that encodes a neural-specific MT-binding protein, to defects in dynein-based functions." (PMID 36476638, 2022). "Variants in the doublecortin gene (DCX) were identified in patients with anterior-biased subcortical band heterotopia and/or X-linked lissencephaly." (PMID 34211111, 2021). "Variants in DCX result in X-linked lissencephaly in males, and its overexpression leads to destabilization of microtubules and inhibition of neurite outgrowth." (PMID 33922640, 2021). "Doublecortin (DCX), a microtubule binding protein required for migration of neural progenitors and associated with X-linked lissencephaly in humans increased over the first 21 DIV after which its transcripts declined." (PMID 32195361, 2020). "Defects in DCX expression are responsible for X-linked lissencephaly and subcortical laminar heterotopia, and mutations in the DCX gene cause malformation of the cerebral neocortex." (PMID 29922247, 2018). "Although DCX is the causative gene for X-linked Lissencephaly in humans, DCX knockout mice display only mild neurodevelopmental delays in the cortex, and cortical lamination in the adult DCX KO mouse is indistinguishable from wild type." (PMID 25904845, 2015). "Doublecortin (DCX) was identified as the gene responsible for X-linked lissencephaly in males and subcortical heterotopia in females." (PMID 20444278, 2010). "Known human neurological disorders associated with the networks, particularly network 2, include X-linked lissencephaly (Online Mendelian Inheritance in Man [OMIM:300067]; DCX), juvenile onset dystonia ([OMIM:607371]; ACTB) and Beckwith-Wiedemann syndrome ([OMIM:130600]; CDKN1C)." (PMID 19799774, 2009). "Key examples include the identification of doublecortin (DCX) as the gene underpinning abnormal cerebral cortex development and morphology in patients with X-linked lissencephaly (XLS); analysis of XLS has underscored the importance of normal neuronal migration during cerebral cortex development." (PMID 41219536, 2025).
Alzheimer disease (12 papers, 2012 to 2025). A progressive, neurodegenerative disease characterized by loss of function and death of nerve cells in several areas of the brain leading to loss of cognitive function such as memory and language. "The mouse model described here is a phenocopy of Alzheimer's disease (AD) in three aspects: reduced NF-κB activity as in AD brains and increased proliferation of immature DCX+ neuronal precursors and progressive cell loss coupled with strong neuroinflammation." (PMID 22312433, 2012). "Immature DCX+ neurons are present in the aging brain but are reduced in Alzheimer’s disease and a recent transcriptomics study suggests that in humans there is a pool of immature neurons that persists into aging." (PMID 41370306, 2025). "Adult neurogenesis is reduced in most amyloid-based mouse models of Alzheimer’s disease and human neurogenesis levels, as measured by DCX expression, inversely correlates with the severity of Alzheimer’s disease." (PMID 41370306, 2025). "The number of doublecortin (Dcx)-positive immature neurons in the dentate gyrus decreases over time, especially in the early stages of Alzheimer’s disease (AD), and is further reduced in later stages of AD." (PMID 35046482, 2022). "Persistent neurogenesis, which is shown by the presence of Nestin+/Sox2+/Ki67+ neural progenitors, DCX+/PCNA+ neuroblasts, and DCX+ immature neurons, was also reported in older adults and to a lesser extent, in Alzheimer disease patients." (PMID 32848586, 2020). "While the presence of these DCX+ neurons decrease with age, they are significantly decrease in patient with Alzheimer’s disease." (PMID 31508196, 2019). "In neurological disorders such as Alzheimer's disease, MSC‐derived exosomes can enhance the expression of DCX and PSA‐NCAM, thereby proving their regenerative potential." (PMID 38783536, 2024). "Evidence supports this theory: Immature neuronal cell markers, including doublecortin and polysialylated nerve cell adhesion molecule (PSA-NCAM), are increased in the DG of patients diagnosed with Alzheimer’s disease." (PMID 22558133, 2012). "They successfully tested several markers (DCX, NeuN, PSA-NCAM, GFAP, PH3, Prox1, calretinin, βIII-tubulin, and calbindin) in healthy brains, and under pathological conditions in brains from patients with Alzheimer’s disease." (PMID 34768919, 2021).
Intellectual disability (12 papers, 2011 to 2024). "Mutations in the human X-linked doublecortin gene (DCX) cause major neocortical disorganization associated with severe intellectual disability and intractable epilepsy." (PMID 24073232, 2013). "DCX haploinsufficiency can lead to various degrees of mental retardation, the extent of retardation is linked to the quantity of arrested neurons in the white matter." (PMID 21249143, 2011). "Genetic variants of DCX, COMT and FMR1 have been linked to neurodevelopmental disorders related to intellectual disability and social behavior." (PMID 35590332, 2022). "Taken together our findings indicate that factors connecting DCX, COMT, and FMR1 in intellectual disability and social behavior may converge at Wnt signaling, neuron migration, and axon and dendrite morphogenesis." (PMID 35590332, 2022).
schizophrenia (9 papers, 2011 to 2024). A major psychotic disorder characterized by abnormalities in the perception or expression of reality. "Numerous schizophrenia-related genes are involved in neuronal differentiation and migration, and abnormal neurogenesis has been linked to DCX expression in schizophrenia patients." (PMID 38336912, 2024). "In patients with schizophrenia the COMTVal allele is associated with smaller temporal and frontal brain areas and as described in the Introduction, DCX variants cause severe lamination defects in the cortical and hippocampus regions." (PMID 35590332, 2022). "In our study of an MK-801-induced schizophrenia animal model, we observed decreased DCX and NeuN gene expression in the HIP, which was also confirmed by the DCX immunohistochemical data." (PMID 35887056, 2022). "Specific to high inflammation schizophrenia, quiescent stem cell marker mRNA (GFAPD) was reduced, whereas neuronal progenitor (ASCL1) and immature neuron marker mRNAs (DCX) were decreased compared to low inflammation control and schizophrenia subgroups." (PMID 34911938, 2021). "qPCR was used to determine expression of DCX mRNA in total RNA from the DLPFC of patients with schizophrenia/schizoaffective disorder (n = 37) and controls (n = 37)." (PMID 21966452, 2011). "Additionally, the age of individuals in the control and schizophrenia population (spanning from 18–80 years) may make subtle alterations in DCX mRNA expression difficult to detect." (PMID 21966452, 2011). "In vivo, we studied the gene expression of DCX, Sox2, BDNF, and NeuN in the SVZ and HIP in an MK-801-induced animal schizophrenia model." (PMID 35887056, 2022). "In an MK-801 schizophrenia model, OLA reversed the MK-801 inhibitory effect on DCX and NeuN and HAL reversed the effect on DCX expression; however, only in the HIP." (PMID 35887056, 2022). "However, in an MK-801-induced schizophrenia animal model, OLA reversed the inhibitory effect of MK-801 on DCX and NeuN and HAL on DCX only in the HIP." (PMID 35887056, 2022). "While we have previously reported an increase in the density of IWMNs in schizophrenia using this cohort, we do not find a change in DCX mRNA in the DLPFC in schizophrenia here." (PMID 21966452, 2011). "DCX mRNA did not display differences in expression in adult schizophrenia patients compared with adult controls, with mean schizophrenia expression being 97.4% of controls (ANCOVA F = 0.31, p = 0.56)." (PMID 21966452, 2011). "Reduced DCX expression in high inflammation schizophrenia could also represent increased migration of immature neurons out of the SEZ, which may relate to increased interstitial white matter neuron density in schizophrenia." (PMID 34911938, 2021). "Accumulation of neurons in the white matter in schizophrenia would be congruent with a negative correlation between DCX mRNA and white matter neuron density and support the hypothesis of a migration deficit in schizophrenia." (PMID 21966452, 2011). "We identified that prolonged stem cell quiescence in high inflammation schizophrenia may diminish the capacity to produce neuronal progenitor cells for brain repair, which is supported by the reduction in neuronal progenitor (ASCL1, DLX6-AS1) and immature neuron marker expression (DCX)." (PMID 34911938, 2021). "Moreover, increased IL6 reduces human hippocampal DCX+ immature neurons through apoptosis in vitro, implying that newly generated neurons may undergo apoptosis in the SEZ in the high inflammation subgroup of schizophrenia." (PMID 34911938, 2021). "However, we report a negative correlation between DCX mRNA expression and white matter neuron density in adult schizophrenia patients, in contrast to a positive correlation in human development where DCX mRNA and white matter neuron density are higher earlier in life." (PMID 21966452, 2011).